CCT5 (chaperonin containing TCP1 subunit 5)
Diseases named in the same sentence as CCT5 in open-access papers (continued):
Sharing a sentence is not in itself a finding about the gene and the disease.
infection (2 papers, 2020 to 2025). The state of being infected such as from the introduction of a foreign agent such as serum, vaccine, antigenic substance or organism. "The stable CCT5-ShRNA1-knockdown cell line and CCT5-ShRNA1-control cell line were infected with FAdV-4 at a multiplicity of infection (MOI) of 0.1." (PMID 40530025, 2025). "Similar to H5N6, either H5N1-DW or H5N1-HM infection was able to result in an increased expression of CCT5 at both mRNA and protein levels." (PMID 33178142, 2020). "Our results showed that NP and CCT5 could colocalize and interact with each other in both overexpression and normal infection conditions." (PMID 33178142, 2020). "The abundance of CCT5 mRNA and protein were elevated in H5N6-infected DF-1 cells, and this parameter is positively correlated with viral replication during the infection course." (PMID 33178142, 2020).
neurologic disorders (2 papers, 2020 to 2022). "This new variant could support the role for CCT5 in neurologic disorders and suggest that a wider phenotypical spectrum of clinical manifestations may be associated with this gene." (PMID 33076433, 2020). "The importance of the CCT5 subunit in preventing neurological disorders was further shown in a different case of early-onset demyelinating neuropathy in which a L224V mutation in the intermediate domain of CCT5 was described." (PMID 35602608, 2022).
myopathies (1 paper, 2023). "Some of the findings discussed in this article suggest that certain histological patterns of skeletal muscle tissue associated with the CCT5 Leu224Val mutation are similar to those found in desmin-related myopathies (DRMs) and in α-crystallinopathy." (PMID 37237456, 2023).
CCT5 also shares sentences with these, for which no sentence is quoted: Alzheimer disease (3 papers); adenocarcinoma (1); amyotrophic lateral sclerosis (1); arrhythmogenic right ventricular dysplasia 5 (1); blastoma (1); brain malformations (1); Charcot-Marie-Tooth disease (1); colon cancer (1); colorectal cancer (1); conduct disorder (1); diabetes (1); esophageal squamous cell carcinoma (1); liver cancer (1); lymph node metastasis (1); neurodegenerative disease (1); non-Hodgkin lymphoma (1); parathyroid adenoma (1); peripheral neuropathy (1); retinoblastoma (1); Spastic paraplegia (1); Spinocerebellar ataxia type 3 (1).